DCC (DCC netrin 1 receptor)
Description:
Receptor for netrin required for axon guidance. Mediates axon attraction of neuronal growth cones in the developing nervous system upon ligand binding. Its association with UNC5 proteins may trigger signaling for axon repulsion. It also acts as a dependence receptor required for apoptosis induction when not associated with netrin ligand. Implicated as a tumor suppressor gene.
Synonyms: IGDCC1; NTN1R1; CRC18; CRCR1; HGPPS2; MRMV1
Tractability: Small molecule: it has a binding pocket of medium quality. Antibody: its Gene Ontology location is reachable by antibodies, with high confidence; UniProt predicts a signal peptide or a membrane-spanning region. PROTAC: UniProt records ubiquitination sites on it; its protein half-life has been measured.
Gene: Protein-coding gene on chromosome 18 (52,340,197 to 53,535,899, forward strand). Ensembl gene ENSG00000187323.
Subcellular location: Membrane
Subcellular location (Human Protein Atlas): Golgi apparatus; Basal body; Centriolar satellite; Centrosome
Pathways (Reactome):
Developmental Biology: DCC mediated attractive signaling; DSCAM interactions; Netrin mediated repulsion signals; Netrin-1 signaling; Regulation of commissural axon pathfinding by SLIT and ROBO; Role of second messengers in netrin-1 signaling
Programmed Cell Death: Caspase activation via Dependence Receptors in the absence of ligand
Gene Ontology:
Molecular function: protein binding; transmembrane signaling receptor activity
Biological process: apoptotic process; axon guidance; axonogenesis; cell-cell adhesion; negative regulation of collateral sprouting; negative regulation of dendrite development; negative regulation of neuron projection development; neuron migration; postsynaptic modulation of chemical synaptic transmission
Cellular component: cell surface; cytosol; plasma membrane; axon; membrane; postsynaptic density membrane; Schaffer collateral - CA1 synapse
Genetic constraint (gnomAD): Loss-of-function variants: 45 observed, 139.33 expected, observed/expected ratio (o/e) 0.32, 90% interval 0.25 to 0.41. The upper end of that interval is the gene's LOEUF score, 0.41, which puts it in group 1 of 6, group 1 being the genes least tolerant of losing a copy. Missense variants: 1,534 observed, 1,642.3 expected, observed/expected ratio (o/e) 0.93, 90% interval 0.89 to 0.97. Synonymous variants: 631 observed, 600.77 expected, observed/expected ratio (o/e) 1.05, 90% interval 0.98 to 1.12.
Gene-disease validity (ClinGen):
ClinGen rates the evidence that DCC causes each of these diseases.
mirror movements 1 and/or agenesis of the corpus callosum (autosomal dominant): Definitive.
Homologues: Orthologues: macaque DCC (99% identical), pig DCC (97% identical), chimpanzee DCC (97% identical), dog DCC (97% identical), mouse Dcc (96% identical), rat Dcc (95% identical), rabbit DCC (94% identical), tropical clawed frog dcc (82% identical), guinea pig DCC (64% identical), zebrafish dcc (55% identical). Paralogues in human: NEO1 (52% identical), SDK2 (18% identical), IGDCC4 (18% identical), SDK1 (18% identical), ROBO1 (18% identical), PRTG (17% identical), ROBO2 (17% identical), ROBO3 (17% identical), CNTN3 (16% identical), CNTN6 (16% identical), NRCAM (16% identical), PTPRQ (16% identical), and 24 more.
Diseases named in the same sentence as DCC in open-access papers:
DCC is named in the same sentence as 141 diseases in open-access papers, as found by Europe PMC text mining. Sharing a sentence is not in itself a finding about the gene and the disease. The quoted sentences say what the papers report.
colorectal cancer (167 papers, 1994 to 2025). A primary or metastatic malignant neoplasm that affects the colon or rectum. "As a positive control, QGP‐1 cells were also transfected with the known tumour suppressor protein Deleted in colorectal cancer (DCC) that encodes the netrin receptor which represses tumour formation when not activated by its ligand netrin." (PMID 39579056, 2025). "For example, DCC is a well-characterized human colorectal cancer suppressor gene, and RUNX1 mutations are closely related to tumorigenesis in human leukemia and breast cancer." (PMID 40833781, 2025). "In humans, the DCC gene is known for its role as a tumor suppressor involved in cancer, with reduction or loss of DCC expression found in the majority of colorectal cancers." (PMID 39677576, 2024). "A third gene of interest in this region is DCC, a gene that codes for the netrin-1 receptor, which has been elaboratively investigated as a tumor suppressor gene for colorectal cancer and has been associated with tumor stage in PC." (PMID 36982172, 2023). "On chromosome 18, the DCC gene is located, and its inactivation is linked to the development and metastasis of colorectal cancer." (PMID 36644780, 2023). "We previously found pathogenic variants in DCC (deleted in colorectal carcinoma) in individuals with congenital MM, thus establishing DCC as the first MM gene." (PMID 37172092, 2023). "Another tumor suppressor gene, which is primarily known as “deleted in colorectal carcinoma” or DCC, encodes the netrin receptor protein and acts as both a conditional oncogene and a conditional tumor suppressor." (PMID 35176183, 2022). "Netrin1 related axonal functions have been linked to two classes of receptors: the deleted in colorectal cancer (DCC) family, including DCC and its orthologue Neogenin-1, and the Unc5s family, including Unc5A." (PMID 34179515, 2021). "Only one gene, DCC (DCC netrin 1 receptor; a.k.a. deleted in colorectal carcinoma), was associated with both male and female MCP." (PMID 33830993, 2021). "Conditional knockdown of deleted in colorectal carcinoma (DCC) within EMX1 cells causes a spectrum of callosal phenotypes." (PMID 33871356, 2021). "Another significant CBP-associated gene variant is the lead SNP rs4384683, an intronic variant in the gene DCC (deleted in colorectal carcinoma)." (PMID 32967120, 2020). "The third significant CBP-associated variant in our study was rs4384683, an intronic variant in the gene DCC (Deleted in Colorectal Carcinoma), which co-localized with regulatory regions in neural embryonic stem cells." (PMID 30261039, 2018). "The deleted in colorectal carcinoma (DCC) gene, which contains four SNPs, encodes the netrin-1 receptor." (PMID 30323194, 2018). "In the presence of β-catenin staining, the scenario can be that the transcriptional effects were initiated by Rac1-dependent nuclear translocation of β-catenin followed by mutation of the Wnt ligand, and deleted in colorectal cancer (DCC)." (PMID 26307342, 2015). "Further, rs2229080, a missense variation replacing Arg to Gly at DCC codon 201, was reported to increase the risk of colorectal cancer and neuroblastoma." (PMID 26602921, 2015). "(c) DCC, the deleted colorectal carcinoma gene, has (as its name implies) been well studied and has been implicated in a number of cancers in addition to colorectal cancer." (PMID 21827660, 2011). "Most studies have linked chromosome 18q LOH in colorectal cancers to a reduction in DCC expression both at the RNA level and at the protein level." (PMID 15956977, 2005). "The data indicating that 18q allelic loss and decreased DCC expression are associated with poor prognosis and possibly decreased response to adjuvant chemotherapy in colorectal cancer patients are interesting and of potential clinical significance." (PMID 15956977, 2005). "Data supporting this proposal included observations that a DCC allele, located on chromosome 18q, was deleted in over 70% of colorectal cancers and a number of other tumours." (PMID 15956977, 2005).
colorectal cancer (continued). "Protein expression of the putative tumour-suppressor gene DCC on chromosome 18q was evaluated in a panel of 16 matched colorectal cancer and normal colonic tissue samples together with DCC mRNA expression and allelic deletions (loss of heterozygosity, LOH)." (PMID 9484816, 1998). "Thirty-one human bladder transitional cell carcinomas (TCCs) were examined for allelic loss at five chromosome 18q loci, including the DCC gene (deleted in colorectal carcinoma) and at chromosome 11p15 in a restriction fragment length polymorphism analysis." (PMID 7917921, 1994). "Apart from mutations in colorectal cancers, studies have highlighted the role of DCC in BC." (PMID 32894086, 2020). "DCC gene is a tumor suppressor gene and is frequently mutated in colorectal carcinomas." (PMID 32894086, 2020). "However, NOTCH1 mutation (HR 4.18, 95% CI 1.65–10.61, P = 0.003), Lysine (K)‐specific methyltransferase (KMT) 2C mutation (HR 2.91, 95% CI 1.09–7.82, P = 0.034) and deleted in colorectal cancer (DCC) mutation (HR 3.72, 95% CI 1.11–12.50, P = 0.034) were associated with shorter OS." (PMID 37864465, 2024). "Background/Objectives: Pathogenic variants in the deleted in colorectal cancer gene (DCC), encoding the Netrin-1 receptor, may lead to mirror movements (MMs) associated with agenesis/dysgenesis of the corpus callosum (ACC) and cognitive and/or neuropsychiatric issues." (PMID 38398422, 2024). "Moreover, DCC rs2229080 polymorphism was reported to occur more frequently in stages C and D in colorectal cancer, and may serve as a prognostic factor for colorectal cancer patients." (PMID 27127179, 2016). "They mediate axonal migration through the binding of the laminin N‐terminal and EGF domains to the transmembrane receptors Deleted in Colorectal Cancer (DCC) and UNC5." (PMID 39648562, 2025). "Specifically, the top two genes specific to MCP were colorectal cancer suppressor (DCC) and sidekick cell adhesion molecule 1 (SDK1), which were enriched in subcortical limbic regions and were involved in mechanisms related to axonogenesis." (PMID 40173244, 2025). "Many studies reported that UNC5 family members and DCC are downregulated at the single gene level because of promoter hypermethylation in colorectal cancer, gastric cancer, renal cell carcinoma, lung cancer, and other solid tumors." (PMID 41407823, 2025). "Adamtsl3 secreted from presynapses binds to the transmembrane protein DCC (Deleted in Colorectal Cancer) and controls its synaptic localization, which is required for the maintenance of GABAergic synapses in the adult brain." (PMID 41036704, 2025). "The peak marker for the length of both the last dorsal spine and the anal spine was located in an intron of the gene Deleted in Colorectal Cancer (DCC), which is a Netrin-1 receptor." (PMID 39677576, 2024). "Our scRNA-seq data revealed prominent expression of deleted in colorectal cancer (DCC) and DSCAM, and weaker expression of Unc5c, Unc5D, and Neogenin." (PMID 39569362, 2024). "The receptor mediating Netrin-1-induced neuronal sprouting, deleted in colorectal cancer (DCC), was found to co-localize with CGRP+ sensory nerve fibers in endplates after LSI surgery." (PMID 37961590, 2024). "The netrin-1 receptor, DCC (Deleted in Colorectal Cancer), is expressed in the dentate hilus and CA3 regions, which serve as origins for projections to the contralateral hippocampus." (PMID 38688719, 2024). "Netrin receptors include the following protein families: UNC5 (Unc-5 Netrin Receptor, UNC5A–D genes) and DCC (Deleted In Colorectal Carcinoma, DCC gene)." (PMID 38646100, 2024). "Among these, many have important roles in regulating the neural progenitors migration, such as deleted in colorectal cancer (DCC), XKR6 and transcription factor 4 (TCF4)." (PMID 36729042, 2023).
colorectal cancer (continued). "The long arm of chromosome 18 spans several confirmed and putative tumor suppressors, including Retinoblastoma-Binding Protein 8 (RBBP8), SMAD family members 2 and 4 (SMAD2/4), and deleted in colorectal cancer (DCC)." (PMID 37954063, 2023). "NTN1 is a pleiotropic secretory glycoprotein that functions as a ligand for two dependence receptors: deleted in colorectal cancer (DCC) and uncoordinated-5 homolog (UNC-5H)." (PMID 37446017, 2023). "Multiple guidance cues, such as netrin‐1 (NTN‐1)/deleted in colorectal carcinoma (DCC), control the guidance of axons and help establish functional neural circuits during development." (PMID 36852451, 2023). "Previous studies demonstrated that both Myosin X and Trio interact with DCC (deleted in colorectal cancer), a receptor of Netrin-1, and the Rac1 activation elicited by Netrin-1 is lost in the Trio-deficient cortex." (PMID 34914033, 2022). "In particular, DCC, the colorectal cancer suppressor, is a prognostic marker in patients with stage II or stage III colorectal cancer." (PMID 36341349, 2022). "Axon guidance receptors such as deleted in colorectal cancer (DCC) contribute to the normal formation of neural circuits, and their mutations can be associated with neural defects." (PMID 35115383, 2022). "Further, the colorectal cancer pathway involved genes which are DCC, Smad2, Smad4, hMLH1, hMSH2, and hMSH3 protein expression were regulated after T. gondii infection." (PMID 36341349, 2022). "The axon guidance signaling pathway is regulated by the netrin-1 receptor DCC(deleted in colorectal cancer), a single-pass transmembrane protein that belongs to the immunoglobulin superfamily, which has been implicated in CRC." (PMID 36551919, 2022). "As examples of DRs relevant to the topic of this review, DCC netrin 1 receptor (DCC, previously named deleted in colorectal carcinoma) and its homologue neogenin (NEO1) are discussed." (PMID 36231134, 2022). "Collagen triple helix repeat containing 1 (CTHRC1) embedded in the Wingless and Int-1/Planar cell polarity (WNT–PCP) pathway, Netrin-1 (NTN1), and deleted in colorectal carcinoma (DCC) provides for SC migration." (PMID 35408800, 2022). "For example, the netrin receptor DCC (deleted in colorectal cancer) is involved in netrin-mediated attraction, whereas the receptor UNC-5 heterodimerizes with DCC to induce repulsion to netrin." (PMID 34068002, 2021). "The netrin receptors consist of various molecules, among which the most prominent members are DCC (deleted in colorectal cancer), the DCC paralogue Neogenin-1 and the UNC5 homologues." (PMID 33511463, 2021). "DCC is located on chromosome 18q; approximately 70% of colorectal cancer cases predicted allelic losses of DCC." (PMID 34638449, 2021). "The receptors for secreted netrins are deleted in colorectal cancer (DCC), the DCC paralogue (neogenin), and the UNC-5 homologues (UNC5A-D)." (PMID 33925862, 2021). "This attraction is mediated by the receptor deleted in colorectal cancer (DCC), which is strongly expressed in the medial habenular axons." (PMID 34169076, 2021). "Netrin 1 (NTN1) and deleted in colorectal carcinoma (DCC) are crucial for remodelling of the interhemispheric fissure (IHF), corpus callosum (CC) and hippocampal commissure (HC) formation." (PMID 33871356, 2021). "Netrin 1 (NTN1) and deleted in colorectal carcinoma (DCC) regulate midline zipper glia (MZG) morphology and spatial distribution." (PMID 33871356, 2021). "Netrin-1 and its receptor “deleted from colorectal cancer” (DCC) have also been confirmed as potential guidance factors." (PMID 32581730, 2020).
colorectal cancer (continued). "As a tumor suppressor, besides colorectal cancer, DCC defect was reported to contribute to the carcinogenesis in many other cancers, such as melanoma, breast, neuroblastoma and hematologic malignancies." (PMID 33088218, 2020). "Neogenin-1 (NEO1) was originally identified as a homologue of the Deleted in Colorectal Cancer (DCC) gene, which acted as a receptor for Netrins and Repulsive Guidance Molecule (RGM) proteins." (PMID 33088218, 2020). "One of these molecules, Netrin-1, and its receptor, DCC (deleted in colorectal cancer), has profound effects, in laboratory animals, on the adolescent expansion of mesocorticolimbic pathways, particularly dopamine." (PMID 31659271, 2020). "Various studies have shown the role of DCC in colorectal carcinoma, gastric, breast, esophageal and prostate cancer." (PMID 32487238, 2020). "The secreted guidance cue netrin (UNC-6 in C. elegans) and its receptors UNC-5 and deleted in colorectal carcinoma (DCC (UNC-40 in C. elegans)) have a critical role in neural development and in the morphogenesis of a number of organs and tissues." (PMID 32781660, 2020). "In our study, the expressions of DCC, Smad2, Smad4, hMLH1, hMSH2, and hMSH3 proteins had been changed, which regulated the colorectal cancer pathway." (PMID 30792708, 2019). "Netrin-1 plays a key role in axon guidance through binding to its receptor, Deleted in Colorectal Cancer (DCC)." (PMID 29479476, 2018). "The Netrin-1 receptor DCC (deleted in colorectal cancer) is responsible for coordinating dopamine axon structure and function in the mPFC." (PMID 29333488, 2018). "The growth cone, a highly specialized dynamic structure at the end of the extending axon, detects these guidance cues via transmembrane receptors, such as the netrin-1 receptors deleted in colorectal cancer (DCC) and UNC5." (PMID 30108487, 2018). "Draxin was expressed in Tbr2 (+) late progenitors and NeuroD1 (+) neuroblasts in the dentate granule cell lineage, whereas expression of its receptor DCC (deleted in colorectal cancer) was mainly detectable in neuroblasts." (PMID 29339781, 2018). "An imbalance in netrin-1 and DCC levels have been cited extensively, where the DCC chromosomal region have been reported to be frequently deleted in colorectal cancer, resulting in low DCC expression and thus cell survival." (PMID 29854303, 2018). "Throughout this journey, PNs express the Ntn1 receptor Deleted in Colorectal Carcinoma (DCC) and are exposed to Ntn1 produced in the floor plate (FP) and ventricular zone." (PMID 29444422, 2018). "Binding of extracellular netrin-1 to its receptors, deleted in colorectal cancer (DCC) and uncoordinated gene 5H2 (UNC5H2), inhibits apoptosis mediated by these receptors." (PMID 29375318, 2017). "Except for STAiR2, which is transcribed from the first intron of the protein coding gene Deleted in Colorectal Cancer (DCC), the other STAiRs are expressed within intergenic regions." (PMID 28801664, 2017). "Instead of binding to Slit1-3, these changed residues now favour mammalian Robo3 forming a complex with the deleted in colorectal cancer (DCC) protein, a Netrin-1 receptor, to transduce Netrin-1 mediated attractive signaling." (PMID 28234971, 2017). "While at least eight netrin receptors have been characterized in the vascular system, netrin-1 function is mainly mediated by two families of receptors: DCC (deleted in colorectal cancer) and UNC5 (uncoordinated-5) families." (PMID 29059224, 2017). "Mutations in the axon guidance cue unc-6/Netrin and its receptor unc-40/Deleted in Colorectal Cancer (DCC) disrupted PLM branch growth along the dorsal-ventral (D-V) axis." (PMID 28384160, 2017). "NET1 promotes endothelial cell nitric oxide production and cell growth and migration in vitro via the receptor deleted in colorectal cancer (DCC)." (PMID 28824923, 2017).